FER1L5 (fer-1 like family member 5)
Description:
Plays a crucial role in male fertility, primarily through its involvement in the acrosome reaction of spermatozoa. Required for the Ca(2+)-activated fusion of the acrosomal membrane with the plasma membrane during the acrosome. May play a role in skeletal muscle cell development by ensuring effective myoblast fusion and facilitating membrane repair.
Synonyms: DKFZp434I0121
Tractability: Antibody: UniProt places it where antibodies can reach, with medium confidence; UniProt predicts a signal peptide or a membrane-spanning region; its Gene Ontology location is reachable by antibodies, with medium confidence; the Human Protein Atlas places it where antibodies can reach.
Gene: Protein-coding gene on chromosome 2 (96,642,737 to 96,704,887, forward strand). Ensembl gene ENSG00000249715.
Subcellular location: Cell membrane; Cytoplasmic vesicle membrane
Subcellular location (Human Protein Atlas): Plasma membrane
Gene Ontology:
Molecular function: calcium ion binding
Biological process: binding of sperm to zona pellucida; membrane fusion involved in acrosome reaction; myoblast fusion; plasma membrane repair; regulation of neurotransmitter secretion
Cellular component: cytoplasmic vesicle membrane; plasma membrane; synaptic vesicle membrane; membrane
Genetic constraint (gnomAD): Loss-of-function variants: 188 observed, 278.01 expected, observed/expected ratio (o/e) 0.68, 90% interval 0.6 to 0.76. The upper end of that interval is the gene's LOEUF score, 0.76, which puts it in group 3 of 6, group 1 being the genes least tolerant of losing a copy. Missense variants: 2,090 observed, 2,640.7 expected, observed/expected ratio (o/e) 0.79, 90% interval 0.76 to 0.82. Synonymous variants: 921 observed, 1,010.2 expected, observed/expected ratio (o/e) 0.91, 90% interval 0.86 to 0.96.
Homologues: Orthologues: chimpanzee FER1L5 (91% identical), dog FER1L5 (79% identical), pig FER1L5 (79% identical), rabbit FER1L5 (76% identical), guinea pig FER1L5 (75% identical), mouse Fer1l5 (73% identical), rat Fer1l5 (72% identical), Caenorhabditis elegans fer-1 (23% identical), Drosophila melanogaster mfr (17% identical). Paralogues in human: MYOF (41% identical), DYSF (41% identical), OTOF (26% identical), FER1L6 (26% identical).
Diseases named in the same sentence as FER1L5 in open-access papers:
FER1L5 is named in the same sentence as 5 diseases in open-access papers, as found by Europe PMC text mining. Sharing a sentence is not in itself a finding about the gene and the disease. The quoted sentences say what the papers report.
dysferlinopathies (1 paper, 2020). "Our data for Fer1L5 will be of great importance in the dysferlinopathy research in near future." (PMID 33182221, 2020). "Given the molecular similarities of Fer1L5 with dysferlin we argue that Fer1L5 may also have a role in the dysferlin repair pathway but further study will give an insight how Fer1L5 functions as a therapeutic target for the dysferlinopathies." (PMID 33182221, 2020).
male infertility (1 paper, 2023). The inability of the male to effect fertilization of an ovum after a specified period of unprotected intercourse. "Revealing FER1L5-associated molecules and their functions may help us understand the etiology of human male infertility." (PMID 36696506, 2023).
oral squamous cell carcinomas (1 paper, 2022). "Our study describes the neoexpression (Juno) and suppression (catsperD, dysferlin, Fer1L5 and otoferlin) of selected genes in oral squamous cell carcinomas (OSCCs)." (PMID 35330493, 2022).
cancer (1 paper, 2022). A tumor composed of atypical neoplastic, often pleomorphic cells that invade other tissues. "Some members of ferlins have already been discovered in human cancer: Dysferlin is significantly associated with pancreatic cancer patient survival, while Otoferlin is correlated to renal clear carcinoma and Fer1L5 to lung adenocarcinomas." (PMID 35330493, 2022). "For some genes (CatsperB, CatsperD, Dysferlin, Fer1L5, Juno), a limited number of published literature referring to cancer is known." (PMID 35330493, 2022).
tumor (1 paper, 2022). "As a result of this approach, particularly Juno as a real tumor marker but also four additional genes, namely CatsperD, Dysferlin, Fer1L5, and Otoferlin remain to be useful in characterizing oral malignancies." (PMID 35330493, 2022).